IL1B (interleukin 1 beta)
Diseases named in the same sentence as IL1B in open-access papers (continued):
Sharing a sentence is not in itself a finding about the gene and the disease.
Insulin resistance (continued). "Juicer Broccoli reduces the levels of IL-1β and IL-6 in cells, which helps to alleviate the decrease of insulin secretion and insulin resistance caused by T2DM, improve the disorder of glucose metabolism, reduce inflammatory response and cardiovascular disease risk." (PMID 38254574, 2024). "Moreover, high concentrations of TNF, IL-1β and IL-6 in circulation cause insulin resistance in hepatocytes and skeletal muscle cells and inhibit insulin production by the pancreas." (PMID 39107476, 2024). "Furthermore, NLRP3 and the secreted IL-1β were reported to be associated with insulin resistance, β-cell dysfunction, and cell death." (PMID 36902422, 2023). "Indeed the overproduction of insulin by beta-cells in an effort to compensate for the insulin resistance causes an important ER stress in beta-cells that activates the NLRP3 inflammasome pathway leading to IL-1B production." (PMID 36247456, 2022). "Insulin resistance which was associated with high circulating levels of IL-12, leptin, and IL-1β could be the most possible reason behind anti-TB immunity." (PMID 35832818, 2022). "Additionally, the elevated expressions of the NLRP3 inflammasome, IL-1β, and IL-18 in adipose tissues are directly associated with insulin resistance and severity of diabetes." (PMID 36187801, 2022). "Both in vitro and in vivo studies have reported the regulation of PAI-1, SAA, and CRP expression to be closely influenced by the pro-inflammatory cytokines, TNF-α, IL-1β and IL-6, as well as hormones such as GCs which are also associated with insulin resistance and T2D." (PMID 35883605, 2022). "Other cytokines that are also associated with obesity and insulin resistance are IL-6 and IL-1β." (PMID 33557218, 2021). "Mounting evidence supports the hypothesis that insulin resistance is caused by a chronic low-grade pro-inflammatory state, with increased circulatory levels of several pro-inflammatory cytokines, including IL-1β." (PMID 34638553, 2021). "IL-1β may cause pancreatic β cell death and dysfunction, thus accelerating the development of insulin resistance." (PMID 32166013, 2020). "Therefore, this shows that hyperglycemia is a strong inducer of NLRP3, and secretion of IL-1β is closely associated with insulin resistance." (PMID 31174550, 2019). "Inflammatory cytokines, e.g., IL-1family members (IL-1α, IL-1β, IL-1Rα, IL-18, IL-33, IL-36, IL-37, and IL-38), are associated with the regulation of atherosclerosis, insulin resistance, and adipose tissue inflammation, all of which are common features of NAFLD." (PMID 31597283, 2019). "Furthermore, IL-1β modulated by TNFα in mouse adipocytes has been reported to cause hepatic insulin resistance." (PMID 30958839, 2019). "Conversely, when IKK2 is superactivated in fasting liver or neonatal liver, where IKK1 is low and FOXO1 activity is high, FOXO1 synergizes with p65/p50 to cause insulin resistance and induce proinflammatory IL-1β, IL-6, CCL2, and CCL20, resulting in progressive inflammation and/or liver fibrosis." (PMID 26219821, 2015). "The increased expression of TNFα and IL-1β likely contribute to the insulin resistance observed in the KI mice, as increased expression of these cytokines in skeletal muscle are associated with higher insulin resistance." (PMID 26405763, 2015). "Given that an ANP-mediated reduction of TNF-α, IL-6 and IL-1β have been linked to reduced insulin resistance, the suppression of these cytokines and potentiation of HO-adiponectin-ANP axis is important for enhanced glucose metabolism and improved kidney function observed in ZDFs." (PMID 24498225, 2014). "Another important cytokine implicated in the development of insulin resistance is IL‐1β." (PMID 24843075, 2014). "This is important because IL-1β is linked to the pathogenesis of insulin resistance." (PMID 23967184, 2013).
Insulin resistance (continued). "Augmented levels of glucose and some associated metabolic derangements (dyslipidemia and/or insulin resistance) may lead to hyperglycemia, which further potentiate the production of IL-1β from β-cells." (PMID 23409091, 2013). "It is recognized that IL-1β is one of the main cytokines implicated in the desensitization of insulin signaling and its genetic invalidation protects mice against diet-induced insulin resistance." (PMID 23316186, 2012). "It is therefore plausible that increased IL-6 expression in adipose tissue after envenomation may be due to TNF-α production, suggesting that TNF-α and IL-1β work in concert to cause insulin resistance." (PMID 22816003, 2012). "Similarly, IL-1β has been implicated in muscle atrophy and insulin resistance." (PMID 38044678, 2024). "In addition, cytokines (TNF-α, IL-6, and IL-1β) may play a role in the hepatic and systemic insulin resistance associated with NASH." (PMID 32316419, 2020). "Importantly, IL-1β secretion per se is associated with insulin resistance." (PMID 32140136, 2020). "Indeed, inflammatory M1 macrophages infiltrating the obese WAT produce proinflammatory mediators (TNF-α, IL-1β, IL-6), which are associated with the development of insulin resistance and the subsequent release of NEFA, leading to systemic lipotoxicity, with effects on the liver and kidney." (PMID 28188334, 2017). "Pro-inflammatory cytokines, such as interleukin-6 (IL-6), tumor necrosis factor-alpha (TNF-α), and interleukin-1β (IL-1β), disrupt insulin signaling, impair β-cell function, and exacerbate insulin resistance." (PMID 41578487, 2026). "For example, therapies that inhibit pro-inflammatory cytokines such as IL-1β have shown potential in reducing insulin resistance and improving overall metabolic health." (PMID 41601721, 2026). "Along with insulin resistance, hepatic inflammation, pro-inflammatory mediation and cirrhosis-associated immune dysfunction, the damaged liver stimulates the release of TNF-α and IL-1β, leading to circulatory and cardiac malfunction." (PMID 40264510, 2025). "This stimulates endothelial cells and immune components, triggering systemic cytokine rises (TNF-α, IL-1β, and IL-6), thereby contributing to atherosclerosis, insulin resistance, hypertension, and dyslipidemia." (PMID 41228440, 2025). "NaP plays a role in regulating insulin resistance, mitochondrial function, and the production of IL-1β, IL-6, and IL-17 in T2DM." (PMID 40636075, 2025). "Quercetin: Inhibits inflammasome activation and IL-1β release, protecting against inflammation-induced insulin resistance." (PMID 40563357, 2025). "The inflammatory cascade is significantly represented by Tumor necrosis factor-alpha (TNF) and Interleukin-1 beta (IL1B), which drive insulin resistance and β-cell dysfunction, and are functionally linked to the AGE-RAGE signaling axis." (PMID 41361572, 2025). "RC also promotes the activation of NLRP3 inflammasome, thereby exacerbating insulin resistance-related inflammation through the upregulation of IL-1β." (PMID 41367915, 2025). "Its activation by hyperglycemia, saturated fatty acids, ceramides, and other endogenous danger signals leads to the secretion of IL-1β and IL-18, promoting insulin resistance, endothelial dysfunction, and atherosclerotic progression." (PMID 40648980, 2025). "The IKK/NF-κB signaling pathway can be activated to increase the production of cytokines (e.g., TNF-α, IL-6, and IL-1β) to promote inflammation and insulin resistance." (PMID 40863244, 2025). "These MΦs secrete pro-inflammatory cytokines such as TNF-α, IL-6, and IL-1β, which inhibit insulin signaling in adipocytes and promote insulin resistance." (PMID 41602577, 2025). "Other relevant cytokines include Interleukin-6 (IL-6) and Interleukin-1 beta (IL1β), which promote insulin resistance by interfering with insulin signaling in peripheral tissues." (PMID 41304906, 2025).
Insulin resistance (continued). "On the other hand, IL-1β administration has been reported to promote insulin resistance in mice, and IL-1β treatment in rats gradually increases blood glucose levels over 48 h." (PMID 39433211, 2025). "The presence of inflammatory infiltrates in hepatic tissue stimulates the secretion of cytokines such as tnf-α and il1b, which contribute to the induction of insulin resistance." (PMID 39794453, 2025). "Collectively, our data indicate that TSH activates inflammatory signaling and promotes the secretion of IL-1α, IL-1β and IL-6 in macrophages, thus aggravating insulin resistance." (PMID 40523992, 2025). "Pro-inflammatory cytokines such as TNF-α, IL-1β, and IL-6 produced by macrophages contribute to insulin resistance and inflammation in diabetes." (PMID 41472730, 2025). "We observed that PA increased several inflammatory genes like IL1B and TNF, which are closely associated with dysfunction of pancreatic islets, adipose, and skeletal muscle related to insulin resistance and hyperglycemia." (PMID 40068774, 2025). "Interleukin-1 beta (IL-1β) plays a critical role in both insulin resistance and pancreatic beta-cell dysfunction." (PMID 40218134, 2025). "Findings: Pro-inflammatory cytokines such as IL-1β, IL-6, and IL-17 contribute to islet inflammation, insulin resistance, and microvascular damage in both T1D and T2D." (PMID 40804870, 2025). "TLR activation produces proinflammatory cytokines (TNF-α, IL-6, and IL-1β) that are essential in developing insulin resistance." (PMID 40076851, 2025). "The levels of blood glucose, lipids, insulin resistance (IR), Interleukin-6 (IL-6), interleukin-1β (IL-1β), tumor necrosis factor-α (TNF-α) were detected, and the pancreatic tissue damage was evaluated by Hematoxylin and eosin (H&E) staining microscope." (PMID 41098781, 2025). "Metabolic syndrome induces insulin resistance and dyslipidemia via an increase in several activators of the hepatic NF-kB pathway, including diverse glycation and oxidation products, IL-1β, and FFA." (PMID 40584440, 2025). "The pro-inflammatory cytokines released in both conditions, such as TNF-α, IL-6, and IL-1β, impair insulin receptor signaling, leading to insulin resistance." (PMID 41007787, 2025). "Another study uncovered that while adipose tissue IL-6 is the main contributor to insulin resistance, IL-1β and TNF-α cooperativity increase IL-6 expression by promoting CREB binding and H3K14 acetylation at the IL-6 promoter region." (PMID 41228440, 2025). "Persistent immune activation in RA leads to excessive production of pro-inflammatory cytokines such as TNF-α, IL-6, and IL-1β, which contribute to hepatic insulin resistance and lipid accumulation." (PMID 40797381, 2025). "In adipose tissue, infiltrating pro-inflammatory macrophages secrete cytokines, including TNF, IL-1β, and IL-6, promoting insulin resistance." (PMID 40648980, 2025). "Early to end glycation markers and IL-1β are pivotal contributors to acute hepatitis and insulin resistance by driving hepatic NF-κB signaling." (PMID 40584440, 2025). "As a result, the risk of acquiring insulin resistance and T2D is higher in individuals with elevated circulating levels of pro-inflammatory mediators (CRP, IL-6, and IL-1β) and in obese individuals." (PMID 40566527, 2025). "These cytokines, including TNF-α, IL-1β, and IL-6, not only exacerbate periodontal tissue destruction but also promote insulin resistance." (PMID 41019448, 2025). "As a result, with insulin resistance, the FFAs alter the formation and secretion of adipokines and inflammatory cytokines, including IL-37, IL-1β, IL-6 and IL-10, resulting in systemic inflammation." (PMID 40264510, 2025). "Increased M1 macrophages secrete pro-inflammatory mediators such as TNF-α, IL-1β and resistin, which act on adipocytes to induce a state of insulin resistance, leading to a positive feedback loop of inflammation and insulin resistance." (PMID 40084146, 2025).
Insulin resistance (continued). "The vitamin combination had the best beneficial effect on lipid metabolism and the vascular system through the most reducing effect on IL-1β, NF-kβ signaling, insulin, insulin resistance, FFAs, MGO, and AGEs." (PMID 39877627, 2025). "A proinflammatory cytokine cascade, including interleukin-6, tumor necrosis factor-alpha, and Interleukin-1 beta, disrupts insulin signaling pathways and leads to insulin resistance." (PMID 40725663, 2025). "Inflammatory mediators like TNF-α and IL-1β can impede insulin signaling pathways, intensifying insulin resistance and ultimately contributing to the advancement of T2DM and the onset of associated complications." (PMID 40519559, 2025). "Subsequently, inflammatory cytokines like tumor necrosis factor alpha (TNFα), interleukin 6 (IL6), and interleukin 1 beta (IL1β) exacerbate insulin resistance and metabolic dysfunction." (PMID 40687133, 2025). "M1 MΦs secrete pro-inflammatory cytokines, such as tumor necrosis factor-alpha (TNF-α), interleukin-6 (IL-6), and interleukin-1 beta (IL-1β), which impair insulin signaling in adipocytes and contribute to insulin resistance." (PMID 41602577, 2025). "Supporting the observation of insulin resistance in KO mice, we found higher expression of inflammatory cytokines, including TNFα, IFNγ, IL-1β, IL-6 and IL-22, in the muscles of KO mice fed with normal diet, compared to the control mice." (PMID 41234234, 2025). "In fact, IL-1β was observed to have an insulin resistance action, and its increased plasma levels, as well as IL-6, increased the risk of developing type 2 diabetes and plays a role in various metabolic processes." (PMID 38254811, 2024). "M1-polarized Kupffer cells and M1 macrophages stimulate the liver to produce triglycerides and activate hepatic stellate cells (HSCs) through the release of IL-1β, further promoting insulin resistance and inflammation." (PMID 39742106, 2024). "Increased levels of IL-1β, IL-6, and TNF-α have been observed in adipose tissue and serum of obese patients, which is associated with insulin resistance in humans and obese mice exposed to HFD." (PMID 39274918, 2024). "Since the discovery of the central role of IL-1β in the pathogenesis of type 2 diabetes, an increasing number of studies have investigated the role of IL-1β blockade in insulin resistance and type 2 diabetes." (PMID 39518962, 2024). "Patients with hyperlipidemia and insulin resistance often exhibit abnormal levels of inflammatory factors, such as IL‐1β and TNF‐α in their adipose tissue and serum compared to healthy individuals." (PMID 39554323, 2024). "Among cytokines, TNF-α, IL-6, IL-18, and IL-1β are the most important in insulin resistance conditions." (PMID 38945951, 2024). "Following strong infection, the synergistic action of IFNγ and IL-1β on pancreatic β cells leads to an increase in insulin production that exceeds the levels required to compensate for skeletal insulin resistance." (PMID 39107476, 2024). "Recent studies have identified IL-1β as a potential contributor to the development of insulin resistance and type 2 diabetes." (PMID 38257186, 2024). "IL-1β can induce insulin resistance by affecting insulin receptor phosphorylation and insulin receptor substrate 1 expression." (PMID 39606781, 2024). "TNF-α impairs insulin action by activating JNK and IKKβ pathways, disrupting insulin signaling, while IL-1β and IL-6 exacerbate insulin resistance by inhibiting receptor functions and glucose uptake." (PMID 39458518, 2024). "The modulation of inflammatory markers like interleukin-1β (IL-1β), tumor necrosis factor-α (TNF-α), and interleukin-6 (IL-6) is crucial in T2DM, as their elevated levels are associated with disease progression, insulin resistance, and β-cell dysfunction." (PMID 39840100, 2024). "TNF-α stimulates IL-1b and IL-6 and increases insulin resistance by phosphorylating insulin receptors." (PMID 39597886, 2024).
Insulin resistance (continued). "Previous studies have shown that the inflammatory process in adipose tissue, initiated by caspase‐1 activation and IL‐1β production in response to energy excess, contributes to glucose intolerance and insulin resistance in obese mice." (PMID 38629728, 2024). "Cytokines produced by these cells, such as TNF, IFNγ and IL-1β, reach the bloodstream and contribute to the development of systemic insulin resistance (IR)." (PMID 39107476, 2024). "Leptin, adiponectin, and resistin are key markers, along with pro-inflammatory cytokines like TNFα, IL-1β, and IL-6, which also play roles in insulin resistance." (PMID 39407941, 2024). "Excessive IL-1β production results in insulin resistance because of a decrease in insulin receptor substrate-1 phosphorylation and reduced IRS-1 expression." (PMID 38945951, 2024). "M1 macrophages do not require insulin for glucose uptake, and the release of ROS and IL-1β contributes to insulin resistance in insulin target cells, including adipocytes, hepatocytes, and myocytes." (PMID 39063184, 2024). "IL-1β is mainly produced by hepatic macrophages and plays a major role in promoting insulin resistance, hepatic lipid accumulation, and inducing hepatic fibrosis." (PMID 39035827, 2024). "Activated immune cells release cytokines such as TNFα and IL-1β, which activate a series of intracellular signalling pathways, altering insulin signalling and inducing insulin resistance." (PMID 38999869, 2024). "After the investigation, body weight, fasting blood sugar (FBS), irisin, insulin, C‐reactive protein (CRP), interleukin‐6 (IL‐6), interleukin‐1 beta (IL‐1β), leptin, adiponectin, and insulin resistance (IR) were assessed." (PMID 39479712, 2024). "Excessive adipose tissue produces a number of proinflammatory cytokines, such as TNF-α, IL-6, and IL-1β, promoting local and systemic chronic low-grade inflammation and resulting in insulin resistance." (PMID 39125786, 2024). "It seemed that different factors were responsible for the MPV increase in NASH subjects with liver fibrosis, such as insulin resistance and AT-related proinflammatory cytokines (including IL-1β, IL-6 and TNFα)." (PMID 36768637, 2023). "Here, we measured the levels of inflammatory cytokines in rats by qPCR, including TNF-α, IL-1β, and IL-6, which are key proinflammatory factors in type 2 diabetes and closely related to insulin resistance." (PMID 37072819, 2023). "This study demonstrated a significant decrease in TNF‐α and IL‐1β levels, a decrease in insulin secretion, a reduction in insulin resistance symptoms, and an increase in HOMA‐β levels in each intervention group." (PMID 37181308, 2023). "The activation of the TNF and IL1B signaling pathways promotes insulin resistance and fat deposition in hepatocytes." (PMID 37602516, 2023). "Proinflammatory mediators such as TNF-α, IL-6, and IL-1β played pivotal roles in the development of insulin resistance in adipose tissue of HFD-fed obese mice." (PMID 37111032, 2023). "Recruited macrophages and Kupffer cells have been associated with insulin resistance and NASH, since they synthesize the well-known pro-inflammatory cytokines interleukin-1 beta (IL-1β), IL-6, and TNF-α." (PMID 37107278, 2023). "At the initial stage of insulin resistance, macrophage-derived interleukin (IL)-1β can stimulate insulin secretion via promoting β-cell proliferation." (PMID 37032781, 2023). "These inflammatory cytokines mediate insulin resistance in metabolic syndrome, especially macrophage-derived IL1-β." (PMID 37175603, 2023). "It was reported that IL-1β disrupts insulin signaling and leads to insulin resistance in hepatocytes via decreasing IRS-1 expression." (PMID 37876013, 2023). "In this regard, it has been demonstrated that in obese mice, global ATG7 haplodeficiency leads to insulin resistance as well as the maturation of pro-IL-1β to IL-1β and increased inflammation." (PMID 37876013, 2023).